SIRT7 (sirtuin 7)
Diseases named in the same sentence as SIRT7 in open-access papers (continued):
Sharing a sentence is not in itself a finding about the gene and the disease.
glioma (continued). "Collectively, lncRNA MEG3 decreased the phosphorylation levels of PI3K/AKT/mTOR pathways by enhancing Sirt7 and finally activates autophagy and improves the prognosis of glioma." (PMID 33029125, 2020). "Second, while our in vivo experiments support the therapeutic potential of SIRT7 inhibition, further studies using orthotopic glioma models and clinical-grade delivery systems with miRNA mimics or inhibitors are needed to verify the applicability of translation." (PMID 41114868, 2025). "Moreover, the upstream regulatory mechanisms that control SIRT7 expression in glioma are not well understood." (PMID 41114868, 2025). "SIRT7 influences glioma progression by regulating IDH1 expression and metabolic pathways." (PMID 40710366, 2025). "To further dissect the functional significance of SIRT7 in glioma tumorigenesis and malignant progression, we next examined whether forced overexpression of SIRT7 could reverse the effects observed in the knockdown experiments." (PMID 41114868, 2025). "First, We evaluated SIRT7 expression levels in normal human astrocytes and glioma cells." (PMID 41114868, 2025). "In addition, reducing the expression of SIRT7 can effectively impede the advancement of glioma cells." (PMID 41114868, 2025). "The levels of SIRT7 were examined in patients with various glioma subtypes." (PMID 41114868, 2025). "Moreover, both in - vitro and in - vivo experiments were carried out to assess the influence of SIRT7 expression levels on the treatment effectiveness of temozolomide (TMZ) in glioma." (PMID 41114868, 2025). "The conclusion drawn from the study is that SIRT7 could be a valuable target for glioma treatment, as inhibiting sirtuin 7 may reduce glioma cell proliferation and invasion, potentially improving patient outcomes." (PMID 40710366, 2025). "In addition, immunohistochemical staining results of mouse glioma tissues provided strong evidence that SIRT7 knockdown enhanced TMZ-induced cytotoxicity in glioblastoma cells." (PMID 41114868, 2025). "However, it is worth noting that SIRT7 expression is downregulated in human HNSCC tissues but upregulated in human glioma tissues, and >50% of gliomas are reported to be GMB." (PMID 36291902, 2022). "Additionally, it implies that re - establishing the expression of miR-148a-3p or directly targeting SIRT7 could be a new therapeutic approach to enhance the prognosis of patients with glioma." (PMID 41114868, 2025). "Since miR-148a-3p inhibited the proliferation of glioma and induced apoptosis in a manner comparable to the consequences of SIRT7 knockdown, rescue experiments were carried out to ascertain whether these effects were specifically mediated through SIRT7." (PMID 41114868, 2025). "Dual-luciferase reporter experiments showed that when miR-148a-3p was overproduced, it markedly reduced the relative luciferase activity of the reporter construct with the wild-type 3’-UTR of SIRT7 in the U251 and LN229 glioma cell lines." (PMID 41114868, 2025). "A team from Jilin University reported that MEG3 inhibited the proliferation and migration of U251 cells by positive regulation of sirtuin 7 (Sirt7) and participates in the suppression of the PI3K/AKT/mTOR axis in glioma." (PMID 36544907, 2022). "MEG3 induces autophagy by upregulation of sirtuin 7 and inhibition on the PI3K/AKT/mTOR pathway in glioma cells." (PMID 33602903, 2021). "Using RT-qPCR and western blot assays, we comparatively analyzed SIRT7 expression between glioma specimens and matched adjacent non-tumoral brain tissues obtained from patients at the Chinese PLA General Hospital." (PMID 41114868, 2025). "SIRT7 regulates IDH1 transcription through its interaction with SREBP1 (Sterol Regulatory Element-binding Protein 1), influencing the production of IDH1 (Isocitrate Dehydrogenase (NADP(+)) 1) in glioma cells and their metabolic reprogramming." (PMID 40710366, 2025).
glioma (continued). "In mouse xenotransplantation models, SIRT7 knockdown inhibits tumor growth and enhances the antitumor effects of TMZ, suggesting that targeting sirtuin 7 could be a promising therapeutic strategy to improve chemotherapy efficacy in glioma patients." (PMID 40710366, 2025). "As SIRT7 is a validated downstream target of miR-148a-3p and promotes glioblastoma cell proliferation and survival, we next investigated whether its suppression could enhance the efficacy of TMZ, a standard chemotherapeutic agent used in glioma treatment." (PMID 41114868, 2025). "The roles of SIRT1, SIRT2, SIRT3, and SIRT7 in glioma are not comprehensively understood." (PMID 36568393, 2022).
liver cancer (15 papers, 2015 to 2024). An epithelial or non-epithelial malignant neoplasm that arises from the liver. "Knockdown of SIRT7 influences the cell cycle and causes a significant increase in the proportion of liver cancer cells that remain in the G1/S phase." (PMID 31196136, 2019). "Mechanisms underlying mPssPC2 NPs mediated inhibition of liver cancer are not fully understood, and whether SIRT7 is responsible for this inhibition is currently under investigation in the lab." (PMID 36678616, 2023). "Sorafenib and SIRT7 inhibitor 2800Z dual-loaded NPs were designed, and we evaluated the efficacy for the treatment of liver cancer." (PMID 36678616, 2023). "P300/cyclic adenosine monophosphate responsive factor (PCAF) acetylated PGK1 K323 to promote its glycolytic enzymatic activity and liver cancer cell metabolism, while Sirtuin 7 deacetylated PGK1 K323 to repress its glycolytic enzymatic activity." (PMID 37226192, 2023). "Researchers also discovered the 2800Z and 40569Z compounds to inhibit SIRT7, which highlights novel therapeutic options against liver cancer." (PMID 37691108, 2023). "Our data thus further approved the combination of a SIRT7 inhibitor and sorafenib for the treatment of liver cancer and provided new drug delivery system for targeted therapy." (PMID 36678616, 2023). "Together with previous work, our data clearly support that targeting SIRT7 potentiates the mechanism-based translational therapeutic strategy for liver cancer management." (PMID 35174171, 2021). "SIRT7 inhibition increased the sensitivity of liver cancer cells to cell death inducing chemotherapeutics such as doxorubicin both in vitro and in vivo." (PMID 31196136, 2019). "Depletion of SIRT7 from multiple liver cancer cell lines significantly increased doxorubicin toxicity while overexpression of SIRT7 largely abolished doxorubicin induced apoptosis." (PMID 31196136, 2019). "More importantly, SIRT7 expression significantly correlated with poor overall survival rate in 364 liver cancer cases." (PMID 31196136, 2019). "They found that SIRT7 knockdown increases the number of liver cancer cells in G1/S phase and delays the cell-cycle transition: p21WAF1/Cip1 expression was increased and cyclin D1 (a G1/S cell cycle regulator) was suppressed in SIRT7 knockdown cells." (PMID 30510540, 2018). "Moreover, in liver cancer, the effects of SIRT7 on the efficacy of the checkpoint inhibitor were found to be dependent on MEF2D." (PMID 39719443, 2024). "Our data thus provides a new platform for a co-delivery system with high affinity to liver tumors and further approved the therapeutic effects of combinational therapy with a SIRT7 inhibitor and sorafenib, which offers a new therapeutic option in treatment of human liver cancer." (PMID 36678616, 2023). "As a result, our leading compounds, 2800Z and 40569Z, showed strong interactions with SIRT7 protein, specifically inhibited SIRT7 deacetylation activity in vitro and in vivo data indicated these compounds induced apoptosis, and increased chemosensitivity to Sorafenib in human liver cancer." (PMID 35174171, 2021). "We have previously identified that elevated SIRT7 expression is associated with chemoresistance in human liver cancer, and pan-SIRT inhibitor enhances chemosensitivity to doxorubicin, which suggested SIRT7 may serve as a therapeutic target of liver cancer." (PMID 35174171, 2021).
liver cancer (continued). "Our data thus strongly suggest SIRT7 represents a druggable target in human cancer and provides valuable preclinical evidences supporting compounds 2800Z and 40569Z as starting leads for the development of new therapeutic options against liver cancer." (PMID 35174171, 2021). "In liver cancer cells, SIRT7 (sirtuin type 7) regulates the acetylation of PGK1 residue Lys323, a mechanism that appears to enhance the efficiency of the glycolytic pathway during the Warburg effect, and consequently promoting cancer proliferation and tumorigenesis." (PMID 33234025, 2020). "In line with its pro-oncogenic functions in HCC, novel specific inhibitors of SIRT7 demonstrated capacity to retard growth of liver cancer cells in in vivo, suggesting that targeting SIRT7 may represent an efficient therapeutic target for this devastating malignancy." (PMID 38383727, 2024). "Moreover, SIRT7 plays a crucial role in promoting liver cancer metastasis." (PMID 38316768, 2024). "By using structure based virtual screening, we developed a specific SIRT7 inhibitor 2800Z, which enhanced the chemosensitivity of sorafenib and reduced the tumor burden, indicating that a combination of sorafenib and 2800Z could serve as new therapeutic option in the treatment of human liver cancer." (PMID 36678616, 2023). "Among them, HDAC7, HDAC4, SIRT7, KAT2A, and HDAC11 were the top five most upregulated genes, indicating that the expression of deacetylation-related genes played a dominant role in liver cancer compared with acetylation-related genes." (PMID 36124029, 2022). "SIRT7 deacylates phosphoglycerate kinase 1 (PGK1), a key enzyme in glycolysis pathway, and suppresses PGK1 enzymatic activity in liver cancer cells." (PMID 30510540, 2018). "Additionally, as detailed below, SIRT7-mediated desuccynilation of the non-histone target PRMT5 appears indispensable for driving progression of liver cancer." (PMID 38383727, 2024).
thyroid cancer (15 papers, 2006 to 2024). "The contribution of SIRT7 to thyroid cancer progression is closely linked to its interaction with another sirtuin family member: SIRT1." (PMID 38383727, 2024). "Of these, SIRT2 and 7 have been associated with particular cancers with widely varying natural histories, SIRT2 with gliomas and SIRT7 with thyroid cancer." (PMID 17003781, 2006). "Besides specific tumors where SIRT7 appears to act as a tumor suppressor, in the vast majority of cases- including liver, pancreas, intestine, colorectal, skin, lung, and thyroid cancers- SIRT7 functions as a prominent pro-tumorigenic factor." (PMID 39036727, 2024). "Through a series of experiments utilizing tissue from patients undergoing thyroidectomy for PTC, cultured human thyroid cancer cell lines, and thyroid cancer xenografts in nude mice, the authors confirmed previous reports of increased expression of SIRT7 in thyroid cancer." (PMID 35406382, 2022). "Additional experiments provided evidence that high levels of SIRT7 exerted stimulated cellular proliferation, invasiveness, and tumor growth in mice carrying implanted human thyroid cancer secondary to the deacetylation of Akt followed by the phosphorylation of the kinase." (PMID 35406382, 2022). "Moreover, the expression of SIRT7 was downregulated in thyroid carcinoma and lower SIRT7 levels were observed in big tumor size." (PMID 30627559, 2018). "As SIRT7 expression is invariably elevated in thyroid cancer cell lines and biopsies, increased expression of SIRT7 may represent an important step in malignant transformation." (PMID 17003781, 2006). "The study suggests that SIRT7 may be targeted in the treatment of aggressive thyroid cancers." (PMID 35406382, 2022). "Remarkably, SIRT7 plays an opposite effect in the activation of the AKT signaling cascade in other malignancies such as lung and thyroid cancers." (PMID 38383727, 2024). "Compared with normal thyroid cancer cells, the expression of SIRT7 was significantly increased in DTC, and the overexpression of SIRT7 and SIRT1 conferred resistance to DTC cells." (PMID 35136826, 2022).
gastric cancer (14 papers, 2016 to 2024). A primary or metastatic malignant neoplasm involving the stomach. "In prostate carcinomas and gastric cancer, SIRT7 overexpression is associated with cancer phenotypes and metastatic diseases." (PMID 33274232, 2020). "Interestingly, the expression of FOXM1 and SIRT7 is demonstrated to be correlated in gastric cancer, and FOXM1 deficiency downregulates SIRT7 in gastric cancer cells." (PMID 37957720, 2023). "In gastric cancers, SIRT7 inhibits apoptosis and autophagy to ensure survival of cancer cells by activating the mTOR-IGF2 signaling cascade." (PMID 38383727, 2024). "Consistently, SIRT7 levels exhibit an observable increase in liver, pancreas, gastric cancer and colorectal tumors as compared to healthy counterparts." (PMID 38383727, 2024). "SIRT7 promotes the growth of gastric cancer cells by inhibiting the expression of the tumor suppressor miR-34a." (PMID 37175631, 2023). "For example, reduced circular RNA circPVT1 retarded gastric cancer growth via microRNA-3666-mediated reduced SIRT7 level." (PMID 33391456, 2021). "Mechanistically, Sirt7 can epigenetically inhibit miR-34a expression by deacetylating H3K18ac, ultimately preventing apoptosis in gastric cancer cells." (PMID 35155211, 2021). "SIRT7 has been shown to promote gastric cancer growth by repressing miR-34a expression through the deacetylation of H3K18 in the promoter region." (PMID 33274232, 2020). "One study revealed that SIRT7 promotes gastric cancer growth and inhibits apoptosis of gastric cancer cells by inhibiting miR-34a activity." (PMID 31285783, 2019). "The results suggested that SIRT4, SIRT6, and SIRT7 were associated with Lauren classification and SIRT3-5 were associated with pStage in gastric cancer." (PMID 29088792, 2017). "It has also been revealed to be correlated to the expression of SIRT7 in gastric cancer." (PMID 37957720, 2023). "However, recent in vitro and in vivo analysis found that SIRT7 promotes gastric cancer growth by deacetylating H3K18ac at the promoter of miRNA-34a, whereas reducing/knocking down SIRT7 inhibits the cancer cell growth." (PMID 28197299, 2017). "Involvement of SIRT7 in GC was reported in only one study that it can promote gastric cancer growth and inhibit apoptosis by epigenetically inhibiting miR-34a and is associated with poor prognosis." (PMID 29088792, 2017).
Obesity (14 papers, 2016 to 2025). Accumulation of substantial excess body fat. "SIRT7 is associated with aging and a number of age-related diseases, including obesity, type 2 diabetes, cardiovascular disease, and cancer, and it has emerged as a therapeutic target for these diseases." (PMID 40243935, 2025). "However, SIRT7 effectively deacetylates multiple targets in vivo, and SIRT7 deficiency in mice results in resistance to obesity, fatty liver, and glucose intolerance." (PMID 40243935, 2025). "Therefore, the purpose of this review was to analyze how SIRT7 is associated with each of the hallmarks of aging, as well as with some of age-associated diseases, such as cardiovascular diseases, obesity, osteoporosis, and cancer." (PMID 35585284, 2022). "Studies using a genetic mouse model showed that liver-specific SIRT7 knockout mice were unsusceptible to high-fat diet-induced fatty liver, obesity, and glucose intolerance, with protection from fatty acid accumulation in the liver." (PMID 40643509, 2025). "Sirt7-knockout mice showed resistance to fatty liver and obesity induced by a high-fat diet, suggesting that SIRT7 promotes lipid accumulation through regulation of fatty acid uptake and triglyceride synthesis." (PMID 39771045, 2024). "We also discuss the possible implications of SIRT7 inhibition in the treatment of metabolic diseases such as type 2 diabetes and obesity." (PMID 38201252, 2023). "Sirt7 KO mice are resistant to HFD-induced obesity, insulin resistance, and glucose intolerance, indicating that SIRT7 deficiency improves insulin sensitivity and glucose homeostasis in vivo." (PMID 38201252, 2023). "In sharp contrast, we demonstrated that Sirt7 knockout (KO) mice are resistant to high-fat diet-induced obesity, glucose intolerance, and fatty liver, suggesting that the loss of SIRT7 induces a metabolically healthy condition." (PMID 36429037, 2022). "Serum FGF21 levels were similar between young Sirt7 KO and control mice, but we demonstrated previously that young Sirt7 KO mice show resistance to high-fat diet-induced obesity, glucose intolerance, and fatty liver." (PMID 36429037, 2022). "For example, miR-204 targets sirtuin 1 (SIRT1) to promote adipogenesis, while miR-93 regulates obesity by inhibiting sirtuin 7 (Sirt7) and T-box 3 (Tbx3)." (PMID 32722316, 2020). "A better understanding of the metabolic roles of SIRT7 might be useful in the development of new strategies for treating metabolic diseases such as obesity and type 2 diabetes." (PMID 38201252, 2023). "SIRT1 and SIRT6 have beneficial effects against metabolic diseases, but we demonstrate that Sirt7 knockout mice are protected from high-fat-diet–induced obesity, glucose intolerance, and fatty liver, suggesting that SIRT7 deficiency plays a beneficial role in metabolic disorders." (PMID 36012298, 2022). "In the same study, it has been shown that lack of SIRT7 increases trigly-ceride content and fatty liver without obesity, as the SIRT7-deficient mice were leaner as compared to controls." (PMID 33806509, 2021). "Therefore, it can be expected that in the future activation of SIRT1 and SIRT2 or inhibition of SIRT7 by appropriate miRNA, may be a therapeutic strategy for the treatment of obesity." (PMID 27104517, 2016). "SIRT7 and SIRT1 promoters' methylation status are not closely associated with the upregulation or downregulation of their mRNA levels induced by obesity." (PMID 30559718, 2018). "A decrease of SIRT7 expression was also observed during obesity in humans, thus, further research is required to elucidate whether or not a difference exists across organisms in the cross-talk between SIRT1 and SIRT7." (PMID 33806509, 2021).